ENSG00000255508 (novel protein)
Gene: Protein-coding gene on chromosome 11 (62,559,603 to 62,591,531, reverse strand). Ensembl gene ENSG00000255508.
Genetic constraint (gnomAD): Missense variants: 644 observed, 702.07 expected, observed/expected ratio (o/e) 0.92, 90% interval 0.86 to 0.98. Synonymous variants: 301 observed, 290.78 expected, observed/expected ratio (o/e) 1.04, 90% interval 0.94 to 1.14.